GAS6 (growth arrest specific 6)
Diseases named in the same sentence as GAS6 in open-access papers (continued):
Sharing a sentence is not in itself a finding about the gene and the disease.
Hypertension (9 papers, 2013 to 2025). The presence of chronic increased pressure in the systemic arterial system. "Gas6 administration induces hallmark PE features, including hypertension, proteinuria, and significant alterations in placental gene expression." (PMID 39996749, 2025). "Four common single nucleotide polymorphisms (SNPs) in the Gas6 gene were genotyped in 984 participants from the Stanford Asia-Pacific Program for Hypertension and Insulin Resistance (SAPPHIRe) family cohort." (PMID 26284522, 2015). "These levels were significantly correlated with markers of inflammation, hypertension, and proteinuria, emphasizing the role of Gas6/AXL signaling in the systemic manifestations of the disease." (PMID 39996749, 2025). "Pregnant rats were administered Gas6 to induce PE-like symptoms such as hypertension and proteinuria; a subset also received the AXL inhibitor R428." (PMID 40862707, 2025). "Recent experimental models have demonstrated that Gas6 administration in pregnant rats induces PE-like symptoms, including hypertension and proteinuria." (PMID 39996749, 2025). "Meanwhile, a higher level of GAS6 in patients of AHF increases the prevalence of hypertension, alongside an incremental proportion of β-blocker, spironolactone and diuretic usage." (PMID 36635690, 2023). "Plasma GAS6 in the acute phase in AHF patients, is closely associated with several risk factors of adverse prognosis in AHF patients, including NYHA functional class, hypertension and renal dysfunction (evaluated by eGFR)." (PMID 36635690, 2023). "The role of Gas6/Axl on hypertension needs further investigation." (PMID 32717722, 2020). "Recent studies have demonstrated that Gas6 amplifies vascular dysfunction by promoting endothelin-1 expression, a potent vasoconstrictor, while simultaneously reducing nitric oxide (NO) bioavailability, leading to increased vascular resistance and hypertension." (PMID 39996749, 2025).
ZIKV infection (9 papers, 2018 to 2023). "In immunocompetent mice, ZIKV infection has been directly linked to increased expression levels of Gas6 and subsequent downregulation of Type 1 IFN response." (PMID 36680287, 2023). "Recent work suggests that patients with neurological complications have high levels of growth arrest-specific 6 (Gas6), which promotes ZIKV infection and downmodulates the type I IFN response." (PMID 34440903, 2021). "The virus has been shown to utilize the receptor tyrosine kinase AXL and its ligand Gas6 for viral entry, albeit contradictory findings on the role of the receptor in ZIKV infection were reported." (PMID 31824472, 2019). "Taken together, these results indicate that Axl-Gas6 engagement and downstream Axl kinase activity are required for robust ZIKV infection of human SC." (PMID 31311882, 2019). "The TAM receptor AXL, through soluble intermediates growth arrest-specific 6 (Gas6) was recently shown to support ZIKV infection of human foreskin fibroblast, glial cells, neural stem cells, and foetal endothelial cells." (PMID 30898036, 2019). "Both AXL and its ligand Gas6 are essential for ZIKV infection and blocking either one of them would inhibit the infection." (PMID 31824472, 2019). "Consistent with anti-Axl treatment, we found that ZIKV infection was reduced by more than 90% in cultures treated with anti-Gas6 compared to the IgG control." (PMID 31311882, 2019). "Since the source of Gas6 is mostly serum present in the culture media, we further assessed ZIKV infection in serum-deprived SC." (PMID 31311882, 2019). "This affinity for astrocytes is likely due to their high expression of AXL, a putative receptor for ZIKV, which interacts with Gas6 to promote ZIKV infection." (PMID 30572570, 2018). "Thus, we reasoned SEV could inhibit ZIKV infection either by blocking PS receptors on cells or by sequestering the Gas6 co-receptor." (PMID 33133043, 2020). "Next, to understand the functional role of AXL in ZIKV infection, we examined the effect of blocking of AXL and growth arrest specific gene-6 (GAS6), ligand for AXL, on ZIKV replication in HBVP." (PMID 32357162, 2020). "Noteworthily, besides serving as an important entry factor for ZIKV infection, AXL and its ligand Gas6 also play an essential role in diverse types of cancer, including GBM which originates from glial cells." (PMID 31824472, 2019). "During ZIKV infection, AXL mediates ZIKV entry indirectly whereby the phosphatidylserine extension on ZIKV lipid membrane binds to Growth arrest-specific 6 (Gas6), one of the ligands for AXL that serves as a bridge for ZIKV and AXL interaction, resulting in clathrin-mediated virus internalization." (PMID 31959174, 2020). "Adding Gas6 at any dose did not reverse inhibition of infection by SEV, nor did it enhance infection of ZIKV alone, indicating that SEV do not impair ZIKV infection by sequestering Gas6." (PMID 33133043, 2020). "Gas6 levels were also higher in ZIKV-infected human patients suffering from neurological complications being treated in Brazil compared to patients that had ZIKV infection but no neurological complications." (PMID 36680287, 2023).
Arthritis (8 papers, 2018 to 2024). Inflammation of a joint. "Next, we quantified the soluble extracellular domain of Axl (sAxl), MerTK (sMerTK), and their ligand Gas6 in the SF obtained at the same time as the synovial biopsy in a subset of early arthritis untreated patients." (PMID 38493215, 2024). "In contrast, increased levels of circulating Gas6 were detected after induction of arthritis by a K/BxN serum-transfer model in mice." (PMID 37242486, 2023). "We have previously shown that overexpression of the TAM receptor ligand genes Pros1 or Gas6 successfully reduced arthritis pathology in a murine model of collagen-induced arthritis." (PMID 37242486, 2023). "At this point, TAM receptor ligands, particularly Gas6, are involved in the resolution of inflammation and present protective effects in experimental arthritis." (PMID 32964059, 2020). "In these studies, Gas6 and Pros1 overexpression decreased arthritis severity, by reducing inflammation and by inhibiting the expression of proinflammatory cytokines." (PMID 32964059, 2020). "In fact, the protective role of both TAM receptor ligands Gas6 and Pros1 has already been described by our group in murine models of arthritis." (PMID 32964059, 2020). "In a mouse model of arthritis, treatment with Gas6 or Pros1 limited inflammatory responses, consequently reducing symptoms." (PMID 31636733, 2019). "We have shown that Axl-/- and Mertk-/- mice develop more severe arthritis whereas activating these receptors by overexpressing their ligands Pros1 and Gas6 ameliorates arthritis." (PMID 30335822, 2018). "From a clinical standpoint, immunoregulators such as IDO, TSG6, and GAS6 might represent therapeutic targets for arthritis post-aav infection." (PMID 37958918, 2023). "Furthermore, studies revealed that targeted delivery of TAM receptor ligand genes Gas6 diminishes the arthritis pathology effectively but the endogenous role of AXL in arthritis development is not fully understood." (PMID 34841689, 2022).
diabetic nephropathy (8 papers, 2012 to 2025). "The Growth arrest-specific 6 gene (Gas6) is a growth factor implicated in the progression of glomerulonephritis and the development of diabetic nephropathy." (PMID 40246828, 2025). "Thus far, Axl and Gas6 signaling is implicated in cell proliferation, migration, and invasion during tumor angiogenesis, as well as in diabetic nephropathy." (PMID 24409287, 2014). "Loss of Gas6 protected against glomerular proliferation, sclerosis and proteinuria in the nephrotoxic nephritis model and reduced mesangial hypertrophy in streptozotocin-induced diabetic nephropathy." (PMID 25019319, 2014). "Conversely, previous studies using Gas6−/− mice have shown a pathological role for Gas6 in nephrotoxic nephritis and streptozotocin-induced diabetic nephropathy." (PMID 25019319, 2014). "There is low expression in the basal state, but Axl and Gas6 are up-regulated in several murine models of renal disease including: Thy1.1 antibody induced glomerulonephritis, nephrotoxic nephritis, streptozotocin-induced diabetic nephropathy and a podocyte ablation model of glomerular albuminuria." (PMID 25019319, 2014). "Previous studies using Gas6-KO mice have shown a pathological role for Gas6 in anti-GBM nephritis and streptozotocin-induced diabetic nephropathy." (PMID 31360267, 2019). "Previous studies have shown the controversial effects of Gas6/AXL in several kidney disease models, e.g., anti-Thy-1-induced nephritis, anti-glomerular basement membrane (GBM)-induced nephritis, streptozotocin-induced diabetic nephropathy, and renal ischemia-reperfusion." (PMID 32324796, 2020).
endothelial dysfunction (8 papers, 2013 to 2025). In vascular diseases, endothelial dysfunction is a systemic pathological state of the endothelium (the inner lining of blood vessels) and can be broadly defined as an imbalance between vasodilating and vasoconstricting substances produced by (or acting on) the endothelium. "We previously demonstrated that plasma Gas6 levels are associated with glucose intolerance, markers of inflammation, and endothelial dysfunction (both in adults and adolescents)." (PMID 26284522, 2015). "Our results showed evidence that hyperglycemia can cause endothelial dysfunction with down-regulation of Gas6/Axl signaling." (PMID 24572151, 2014). "In this study, we first confirmed plasma Gas6 molecules are inversely associated with glucose values and endothelial dysfunction markers in human." (PMID 24572151, 2014). "Our report also elucidates plasma Gas6 levels are associated with altered glucose tolerance, inflammation, and endothelial dysfunction." (PMID 24572151, 2014). "In CABG patients, plasma Gas6 levels were associated with glucose levels, endothelial dysfunction markers, and the predicted operative mortality rate." (PMID 24236135, 2013). "Plasma Gas6 levels have been shown to be associated with endothelial dysfunction markers and cardiovascular events." (PMID 24236135, 2013). "Our previous study has also shown that plasma Gas6 levels are significantly lower among patients with new onset of type-2 diabetes and are associated with glucose levels, inflammation, and endothelial dysfunction markers." (PMID 24236135, 2013). "Our previous study has also shown that plasma Gas6 protein is associated with altered glucose tolerance, inflammation, and endothelial dysfunction markers." (PMID 24236135, 2013). "We concluded that plasma Gas6 is associated with fasting glucose, endothelial dysfunction markers, sAxl values, and vascular Gas6 expression in CABG patients, and it predicts the operative mortality of these patients." (PMID 24236135, 2013). "Plasma Gas6 concentration may represent an independent risk factor of type 2 diabetes, and a potential surrogate marker of inflammation and endothelial dysfunction." (PMID 24572151, 2014). "A further study also confirms that excessive sAxl can bind to Gas6 to reduce free Gas6 levels in blood circulation, thus inhibiting Gas6/Axl-mediated signaling pathway, and sAxl is considered to represent a biomarker of endothelial dysfunction." (PMID 34326776, 2021). "In the present study, we dissected the role of Gas6/Axl and its downstream signaling within HG-induced endothelial dysfunction." (PMID 24572151, 2014). "In all subjects as a whole, the plasma Gas6 value was significantly and inversely correlated with glucose status and endothelial dysfunction markers." (PMID 24572151, 2014). "The aim of this study was to explore the role of Gas6/Axl system in high glucose (HG)-induced endothelial dysfunction." (PMID 24572151, 2014). "The results showed that CABG patients with high plasma Gas6 levels appeared to have lower fasting glucose, endothelial dysfunction markers, and predicted operative mortality rates." (PMID 24236135, 2013). "Our study revealed that plasma Gas6 levels were not only negatively correlated with the endothelial dysfunction markers E-selectin and VCAM-1 but also negatively correlated with the predicted mortality rate calculated from the EuroSCORE II system." (PMID 24236135, 2013). "In the ward cohort, we found multiple correlations between LUS score and markers for endothelial dysfunction and immune activation, whereas in the ICU cohort, only GAS6 seemed to be correlated with LUS score." (PMID 38396460, 2024). "A previous study reports hyperglycemia-induced human endothelial dysfunction via an increase in intercellular adhesion molecule-1 (ICAM-1), VCAM-1 expression, and reduced Gas6/Axl expression." (PMID 34326776, 2021).
endothelial dysfunction (continued). "Although the effects of these genetic variants on subsequent progression to T2D remain unclear, our previous findings suggest that plasma Gas6 levels may protect against T2D, elevated FPG, inflammation, and endothelial dysfunction." (PMID 26284522, 2015). "When this complex system does not function adequately, proteins like MGP and Gas6 will function improperly, which may favor vascular calcification and endothelial dysfunction and therefore could affect stroke recovery." (PMID 41155747, 2025). "However, the plausible role of Gas6/Axl molecules and its downstream signaling in the context of hyperglycemia and endothelial dysfunction has never been explored." (PMID 24572151, 2014).
osteosarcoma (8 papers, 2013 to 2022). A usually aggressive malignant bone-forming mesenchymal neoplasm, predominantly affecting adolescents and young adults. "In osteosarcoma cells, GAS6-induced AXL activation protected serum starved cancer cells from apoptosis, whereas knockdown of AXL inhibited cell proliferation and increased apoptosis." (PMID 31694201, 2019). "For instance, in the osteosarcoma cell lines MG63 and U2OS, Axl activation by recombinant human Gas6 can protect tumour cells from apoptosis caused by serum starvation, and knockdown of Axl inhibits osteosarcoma cell proliferation and induces apoptosis." (PMID 29386018, 2018). "We identified IGFBP4 and GAS6 as the most downregulated genes in osteosarcoma (average log fold changes of -4.43 and -4.29, respectively)." (PMID 23688189, 2013). "In the bone microenvironment, Shiozawa and colleagues demonstrated that Gas6 may be more abundantly secreted in human osteoblasts than osteosarcoma cells." (PMID 33791875, 2021). "Both IGFBP4 and GAS6 show high variability in expression in osteosarcoma cell lines and biopsies." (PMID 23688189, 2013). "GAS6 and related AXL receptor tyrosine kinase have been shown to be involved in metastasis of renal cancer and osteosarcoma." (PMID 26954680, 2016). "Both IGFBP4 and GAS6 expression have previously been shown to be downregulated in osteosarcoma cell lines (IGFBP4 in MG63, GAS6 in MG63 and SAOS2 cells)." (PMID 23688189, 2013). "IGFBP4 and GAS6, which code for proteins that inhibit IGF1R signaling, showed the highest significant downregulation (log fold changes <−4) in a four-way analysis, in which osteosarcoma pretreatment biopsies or cell lines were compared with osteoblastic cultures (n=3) or MSCs (n=12)." (PMID 23688189, 2013).
Stroke (8 papers, 2011 to 2025). Sudden impairment of blood flow to a part of the brain due to occlusion or rupture of an artery to the brain. "Munoz and colleagues identified several single nucleotide polymorphisms (SNPs) of the Gas6 gene, and found an association between SNP c.843 + 7G > A in intron 8 (rs8191974) and stroke." (PMID 26284522, 2015). "Although GAS6 gene polymorphisms are reported to be associated with stroke, acute coronary syndrome, and type 2 diabetes, to our knowledge, both GAS6 and AXL gene polymorphisms associated with childhood obesity have not yet been identified." (PMID 24696684, 2014). "Finally, Gas6 and TAM receptors are affected by genetic polymorphisms, and specific Gas6 haplotypes can protect against both stroke and acute coronary events." (PMID 34836355, 2021). "Interestingly, a previous study found that the A allele or the AA genotype of GAS6 rs8191974 is associated with decreased risk of stroke." (PMID 24696684, 2014). "Endogenous expression of Axl and Gas6 increased in microglia/macrophage after stroke, while intranasal injection of recombinant Gas6 (rGas6) reduced the neurological deficits through inhibiting neuroinflammation by inhibiting TLR/TRAF/NF-kappaB pathway." (PMID 35082781, 2021). "The evidence we establish for a regulatory role of at least two SVZ endogenous VKDPs, protein S and Gas6, for neural precursors proliferation should be taken into account for the use of warfarin for treating stroke and cerebral ischemia." (PMID 22290807, 2012). "Moreover, the possible protective roles of specific haplotypes of the Gas6 gene against stroke have been reported." (PMID 26284522, 2015).
bladder cancer (7 papers, 2019 to 2024). "In addition, the overexpression of Gas6 is usually associated with poor clinical prognosis, including in ovarian, lung adenocarcinoma, pancreatic, and bladder cancers." (PMID 39451556, 2024). "In fact, this ability to induce EMT-related genes can be harvested by malignant bladder cancer cells to facilitate cancer progression, and this occurs through the GAS6-AXL axis—a signaling pathway previously implicated in tumor cell proliferation, EMT, and immune evasion." (PMID 38137547, 2023). "Because GAS6 has the capacity to stimulate AXL-mediated chemotaxis, malignant bladder cancer cells can utilize GAS6-AXL signaling to recruit PD1hi CD200hi CD4+ exhausted T cells and indirectly promote EMT." (PMID 38137547, 2023). "In addition, it has been shown that Gas6 is highly expressed in bladder cancer and is significantly correlated with PI3K expression." (PMID 39451556, 2024). "In addition, we also found that bladder cancer cells can recruit PD1hi CD200hi CD4+ exhausted T cells to promote EMT by enhancing m6A‐mediated GAS6." (PMID 37313656, 2023). "Furthermore, bladder cancer cells have the capacity to upregulate GAS6 expression by modifying m6A via METTL3 activity." (PMID 38137547, 2023). "Finally, we observed that malignant cells can recruit PD1hi CD200hi CD4+ exhausted T cells to induce EMT in bladder cancer cells by releasing m6A‐mediated GAS6." (PMID 37313656, 2023). "The mechanisms by which bladder cancer cells upregulate GAS6 expression are also discussed." (PMID 37313656, 2023). "Overall, the PD1hi CD200hi CD4+ T cells might be recruited and contribute to the EMT of bladder cancer cells through m6A‐mediated GAS6." (PMID 37313656, 2023). "Additionally, we verified that m6A can regulate GAS6 expression through METTL3 in bladder cancer cells using immunoprecipitation experiments and in vitro experiments." (PMID 37313656, 2023). "In conclusion, these findings suggested that METTL3 could regulate GAS6 expression in an m6A‐dependent manner in bladder cancer cells." (PMID 37313656, 2023). "GAS6 might play a pivotal role in the development of bladder cancer, being a potential target for its treatment." (PMID 32899501, 2020). "Next, GAS6 expression at both RNA and protein levels was reduced after METTL3 knock‐down in the bladder cancer cell Lines T24 and UMUC3." (PMID 37313656, 2023). "A recent study reported that overexpression of GAS6, a potent TAM ligand stimulates proliferation and invasiveness of bladder cancer cells." (PMID 35955805, 2022). "Another study has demonstrated that overexpression of GAS6, a potent TAM ligand stimulates proliferation and invasiveness of bladder cancer cells." (PMID 35955805, 2022). "The results above indicated that the GAS6–AXL axis might interact with the PD1hi CD200hi CD4 exhausted T cells, trigger EMT and promote bladder cancer progression." (PMID 37313656, 2023). "Highly consistent with our single-cell data analysis, a previous study reported that bladder cancer cells with LGALS1 silencing and GAS6 depletion could reduce cell proliferation, lower invasive capability, and lower clonogenicity (PMID: 27440446 and PMID: 32547108)." (PMID 37745978, 2023).